KDM4A (lysine demethylase 4A)
Diseases named in the same sentence as KDM4A in open-access papers (continued):
Sharing a sentence is not in itself a finding about the gene and the disease.
triple-negative breast carcinoma (3 papers, 2020 to 2025). An invasive breast carcinoma which is negative for expression of estrogen receptor (ER), progesterone receptor (PR), and human epidermal growth factor receptor 2 (HER2).
Anxiety (2 papers, 2020 to 2024). Intense feelings of nervousness, tension, or panic often arise in response to interpersonal stresses. "The Kdm4a cKO mice showed normal locomotor activity in the open field test and unaltered anxiety levels in the elevated plus maze test." (PMID 39003305, 2024).
endometrial cancer (2 papers, 2015 to 2021). Primary or metastatic malignant neoplasm involving the endometrium (mucous membrane that lines the endometrial cavity). "Expression of KDM4B and KDM4A is higher in endometrial cancer tissue compared to normal endometrium tissue." (PMID 33669182, 2021).
glioblastoma (2 papers, 2018 to 2021). The most malignant astrocytic tumor (WHO grade IV). "Immunoblot analysis revealed that KDM4C and KDM4D protein levels were highly expressed in most of the glioblastoma cell lines, whereas the protein levels of KDM4A and KDM4B were very low or not detected." (PMID 33462212, 2021). "KDM4C and c-Myc expressions were positively correlated, whereas those of KDM4A, KDM4B, and KDM4D did not correlate with c-Myc in glioblastoma." (PMID 33462212, 2021).
lymph node metastasis (2 papers, 2014 to 2017). "In Kaplan-Meier analysis, KDM4A expression, large tumor size, late clinical TNM stage, and positive lymph node metastasis were significant risk factors in patients who underwent OSCC resection." (PMID 29113308, 2017). "The expression of KDM4A was significantly correlated with lymph node metastasis and TNM stage." (PMID 29113308, 2017).
lymphoma (2 papers, 2020 to 2022). A malignant (clonal) proliferation of B- lymphocytes or T- lymphocytes which involves the lymph nodes, bone marrow and/or extranodal sites. "We found that in addition to inhibiting cell apoptosis, KDM4A also promotes cell movement and angiogenesis, the cellular functions contributing to lymphoma dissemination." (PMID 35914074, 2022).
myeloid leukemia (2 papers, 2021 to 2022). A clonal proliferation of myeloid cells and their precursors in the bone marrow, peripheral blood, and spleen. "Herein we demonstrate that KDM4A KD induces AML apoptosis by a unique mechanism to KDM4C in myeloid leukemia." (PMID 34083515, 2021). "Simultaneous knockout (KO) of all three members of the Kdm4 family (kdm4a/b/c) in mice attenuates MLL-AF9 AML9, indicating roles for the Kdm4 family in murine myeloid leukemia." (PMID 34083515, 2021).
oral cancer (2 papers, 2017 to 2022). "Acknowledged predictors of oral cancer, including clinicopathological indicators, were added into the models to accurately examine the incremental value of KDM4A." (PMID 29113308, 2017). "Moreover, KDM4A was differentially expressed in oral cancer tissues from patients characterized by different survival times, and the increased expression of KDM4A was also associated with the advanced TNM stage, indicating that KDM4A may have significance for the prognosis of OSCC patients." (PMID 35326475, 2022).
osteoporosis (2 papers, 2023 to 2024). A condition of reduced bone mass, with decreased cortical thickness and a decrease in the number and size of the trabeculae of cancellous bone (but normal chemical composition), resulting in increased fracture incidence. "MiR−137/KDM4A axis suppressed the osteogenic differentiation of human BMSCs and exacerbating osteoporosis by activating TLR4/NF−κB pathway." (PMID 38504994, 2024). "A more recent study showed that the miR−137/KDM4A axis suppressed the osteogenic differentiation of human BMSCs (promoted osteoclast) and exacerbated osteoporosis by activating the TLR4/NF−κB pathway." (PMID 38504994, 2024). "MiR-137 enhances the activity of the TLR4/NF-κB pathway by targeting KDM4A, thereby inhibiting the osteogenic differentiation of hBMSCs and exacerbating osteoporosis." (PMID 37344864, 2023). "Therefore, we speculate that miR-137 may activate TLR4/NF-κB pathway by targeting KDM4A, thereby inhibiting the osteogenic differentiation of mesenchymal stem cells and worsening osteoporosis." (PMID 37344864, 2023).
uterine corpus endometrioid carcinoma (2 papers, 2015 to 2022). "As for the KDM4A-CNP0371131 complex (which had the highest FRED/Chemgauss4 score) we observed that CNP0371131 was exclusive for KDM4A; thus, could be used as a treatment for cancers where only KDM4A is deregulated, such as Uterine Corpus Endometrioid Carcinoma and Testicular Germ Cell Tumor." (PMID 35480330, 2022). "cBioPortal was used to identify relationships between KDM4B and KDM4A expression and disease-free survival (DFS) of uterine corpus endometrioid carcinoma (UCEC) patients (n = 333) in an independent dataset from TCGA network." (PMID 26397136, 2015).
viral infection (2 papers, 2020 to 2024). "To eliminate the influence of viral infection, we generated a conditional knockout (cKO) mice model to induce Kdm4a KO in brain." (PMID 39003305, 2024).
adrenocortical cancer (1 paper, 2022). "Moreover, KDM4A, B, and D are relevant for Adrenocortical Cancer and Thyroid Carcinoma; thus the COCONUT CNP0002425, CNP0299696, and CNP216191 compounds are prominent candidates for the treatment of those neoplasms." (PMID 35480330, 2022).
alcohol dependence (1 paper, 2021). Physical and psychological dependence on alcohol. "Interactions with KDM4A included both dopamine agonists and agents, as well as adrenergic agents, drugs used in alcohol dependence such as disulfiram, opioid anesthetics, such as sufentanil citrate, and antidepressants." (PMID 34728798, 2021).
allergic disease (1 paper, 2025). An immune response that occurs following re-exposure to an innocuous antigen, and that requires the presence of existing antibodies against that antigen. "Given that Th2 polarization is a hallmark pathological feature of allergic diseases, we investigated whether Kdm4a gene ablation in CD4+ T cells affected allergic responses in the airways." (PMID 41403832, 2025).
alopecia areata (1 paper, 2024). Loss of scalp and body hair involving microscopically inflammatory patchy areas. "It shows that alopecia areata increased KDM5A, MLL, SETD7, and G9A expression, as well as reduced LSD1, KDM4A, and KDM4B expression." (PMID 39046182, 2024).
bladder tumor (1 paper, 2024). "Our preliminary discoveries suggest a noteworthy role of Kdm4a in sustaining the growth of bladder tumor organoids within the Kdm4 family." (PMID 39461328, 2024).
brain cancer (1 paper, 2016). A primary or metastatic malignant neoplasm affecting the brain. "The novel PTEN-independent mode of mTORC1/2 activation via mutated IDH/2HG/KDM4A/DEPTOR revealed here may provide an additional molecular explanation for the oncogenic activity of IDH1/2 mutation in brain cancer." (PMID 27624942, 2016).
brain injury (1 paper, 2023). Acute and chronic (see also brain INJURIES, CHRONIC) injuries to the brain, including the cerebral hemispheres, CEREBELLUM, and brain STEM. "Our results show that KDM4A plays an important role in TBI + HS-induced brain injury, which is at least partly achieved by activation of the microglia." (PMID 36869312, 2023). "Accordingly, in this work, we implied that KDM4A may play a key role in microglia M1 polarization in the TBI + HS induced brain injury." (PMID 36869312, 2023).
breast tumor (1 paper, 2019). "KDM4A and KDM4B are considered promising therapeutic targets for prostate and breast tumor growth based on their functions as coactivators of androgen receptor and estrogen receptor, respectively." (PMID 30683841, 2019).
cardiac interstitial fibrosis (1 paper, 2025). "Moreover, fibroblast specific gain‐ and loss‐of‐function assays showed that Kdm4a promoted the premature senescence of fibroblasts and cardiac interstitial fibrosis, contributing to cardiac remodeling in the advanced stage after MI, without influencing early cardiac rupture." (PMID 40231733, 2025). "Excitingly, we further identified Kdm4a as a crucial promoter of premature senescence in fibroblasts, which induces cardiac interstitial fibrosis." (PMID 40231733, 2025). "Another important finding in our study is that Kdm4a is a critical inducer of premature senescent fibroblasts, leading to cardiac interstitial fibrosis." (PMID 40231733, 2025). "Kdm4a downregulation restrains excessive cardiac interstitial fibrosis and remodeling by depressing the premature senescence of fibroblasts in the advanced stage after MI but does not affect early ventricular rupture." (PMID 40231733, 2025). "Taken together, these findings strongly suggest that Kdm4a is a key driver of cardiac interstitial fibrosis post‐MI." (PMID 40231733, 2025). "We further revealed that Kdm4a induces the premature senescence of fibroblasts by depressing cell autophagy through the H3K9me3 modification of Trim44, resulting in cardiac interstitial fibrosis." (PMID 40231733, 2025). "It verified that Kdm4a downregulation promotes autophagy in premature senescent fibroblasts by increasing the H3K9m3 modification of the Trim44 promoter, significantly suppressing premature senescence in fibroblasts, and ultimately reducing cardiac interstitial fibrosis." (PMID 40231733, 2025). "In conclusion, premature senescent fibroblasts play a pivotal role in promoting cardiac interstitial fibrosis in the advanced stage after MI without affecting replacement fibrosis, which can be inhibited by Kdm4a deletion through Trim44‐mediated autophagy of premature senescent fibroblasts." (PMID 40231733, 2025).
diabetes (1 paper, 2025). "Our findings identify KDM4A as a key epigenetic regulator, suggesting that its modulation could enhance the generation of functional β cells for regenerative medicine in diabetes." (PMID 41244052, 2025). "If knockdown experiments revealed specific repression effects during differentiation, it is plausible that KDM4A overexpression may help optimize laboratory methodologies for generating pancreatic β-cells, potentially advancing regenerative therapies for diabetes mellitus." (PMID 41244052, 2025). "These strategies will help establish whether KDM4A activity not only enables β-cell differentiation but also prevents off-target lineage activation, with direct implications for improving stem cell-based therapies for diabetes." (PMID 41244052, 2025). "Using KDM4A knockdown iPSCs, we test whether impaired H3K9me3 clearance disrupts endocrine specification and β-cell maturation, offering insights into the epigenetic barriers that limit the generation of functional cells for diabetes therapy." (PMID 41244052, 2025).
diffuse intrinsic pontine glioma (1 paper, 2017). A neuroglial tumor that arises from the middle portion of the brain stem. "Beside KDM1, KDM4A and KDM5A/5B are up-regulated in TMZ-resistant GB cells, KDM4B is up-regulated in response to irradiation and KDM6B was identified as a possible therapeutic target in the childhood Diffuse Intrinsic Pontine Glioma (DIPG)." (PMID 28432280, 2017).
endometriosis (1 paper, 2023). The growth of functional endometrial tissue in anatomic sites outside the uterine body. "Seven genes, namely, APPL1, CSNK2A1, ERG, KDM4A, SMARCC1, SUZ12 and TRIM25, were selected to establish the diagnostic model for endometriosis, and a nomogram was constructed based on them." (PMID 36860677, 2023).
fibrosis (1 paper, 2025). the formation of excess fibrous connective tissue in an organ or tissue in a reparative or reactive process. "Moreover, we found that Kdm4a increases the expression of SASP factors from premature senescent fibroblasts, then accelerating interstitial fibrosis through various classic fibrosis‐associated pathways, including ECM‒receptor interactions, the TGF‒β signaling pathway, and the TNF signaling pathway." (PMID 40231733, 2025). "Our findings indicate that targeting Kdm4a‐induced premature senescent fibroblasts might be a clinically valuable therapy that restricts excessive cardiac fibrosis and does not promote ventricular rupture after MI." (PMID 40231733, 2025).
injury (1 paper, 2023). Damage inflicted on the body as the direct or indirect result of an external force, with or without disruption of structural continuity. "Therefore, we explored the role of KDM4A in the TBI + HS combined model induced brain injury." (PMID 36869312, 2023).
Intellectual disability (1 paper, 2025). "The two patients in our cohort with the same variant in KDM4A have varying levels of intellectual disability." (PMID 40577202, 2025).
lymphoproliferative disorders (1 paper, 2022). "Among them, IL-10, an immunosuppressive cytokine contributing to viral persistence in and pathogenesis of KSHV-associated lymphoproliferative disorders (33, –, 35), showed a consistent induction by KSHV reactivation (>1.5-fold) in KDM4A-WT-, but not in KDM4A-K471R-expressing cells." (PMID 35914074, 2022).
melanoma (1 paper, 2025). A malignant, usually aggressive tumor composed of atypical, neoplastic melanocytes. "KDM4A and KDM5B can be considered proto-oncogenes, and targeting these demethylases could potentially result in tumor suppression, which makes them attractive therapeutic targets in melanoma." (PMID 40075679, 2025).
metastatic cancers (1 paper, 2024). A carcinoma which has spread from the original site of growth to another anatomic site. "This appears to be characteristic of KDM4 inhibitors, as QC8222 has entered a trial for advanced metastatic cancers, and the pan-KDM inhibitor JIB-04 is currently in clinical trial against breast leptomeningeal carcinomatosis, due to KDM4A and C inhibition." (PMID 38325742, 2024).
myeloid malignancies (1 paper, 2021). "Thus, KDM4A is a promising target for novel diagnostic and therapeutic approaches in myeloid malignancies." (PMID 34944554, 2021).
Myocardial fibrosis (1 paper, 2025). "We further investigated the effects of Kdm4a on myocardial fibrosis after MI." (PMID 40231733, 2025).
opioid use disorder (1 paper, 2023). A substance-related disorder that involves the recurring use of opioids despite negative consequences. "We also detected associations near XKR6 and AFF3, which have been recently implicated in externalizing psychopathology, and PTPRF and KDM4A, recently implicated in problematic opioid use and opioid use disorder." (PMID 37173343, 2023).
schizophrenia (1 paper, 2023). A major psychotic disorder characterized by abnormalities in the perception or expression of reality. "As expected, there was also limited concordance between schizophrenia and ADHD (r = 0.0705), particularly for downregulated genes, and six (MAD1L1, KDM4A, IPO13, ATP6V0B, DPH2, PTPRF) of the nine placental genes associated with ADHD were also significantly associated with schizophrenia." (PMID 37188697, 2023).
squamous cell carcinoma of the cervix (1 paper, 2022). "By searching the Oncomine database, we found that KDM4A was highly expressed in cervical squamous cell carcinoma compared with that in the normal cervical epithelial tissues (p< 0.05)." (PMID 35287356, 2022). "Our result showed the KDM4A expression was gradually increased in squamous cell carcinoma of the cervix and in SiHa and Hela cells treated with hypoxia for 0.5-12 h with the prolongation of hypoxia time." (PMID 35287356, 2022).
Stroke (1 paper, 2025). Sudden impairment of blood flow to a part of the brain due to occlusion or rupture of an artery to the brain. "This study explores the molecular mechanisms through which lysine-specific histone demethylase 4 (KDM4A) regulates microglial polarization postischemic stroke." (PMID 40999902, 2025).
tauopathies (1 paper, 2022). "KDM4A (and other JmjC KDMs) could thus be associated with heterochromatin alteration in tauopathies of AD by catalyzing H3K9me2 demethylation." (PMID 35852137, 2022).